HLA-B (major histocompatibility complex, class I, B)
Diseases named in the same sentence as HLA-B in open-access papers (continued):
Sharing a sentence is not in itself a finding about the gene and the disease.
ocular toxoplasmosis (2 papers, 2015 to 2020). Ocular toxoplasmosis is an infection in the eye caused by the parasite, Toxoplasm a gondii. "The MICA*002~HLA-B*35 haplotype was associated with increased risk of developing ocular toxoplasmosis, while the MICA*008~HLA-C*07 haplotype was associated with protection against the ocular manifestations of toxoplasmosis." (PMID 26672749, 2015). "The association between MICA and ocular toxoplasmosis was observed only when the linkage disequilibrium between the HLA-B and HLA-C loci was analysed." (PMID 26672749, 2015).
plague (2 papers, 2019 to 2021). Plague is a severe bacterial infection caused by the gram-negative bacterium Yersinia pestis. "We observed a lower frequency of the HLA-B allotypes that can interact with KIR3DL1 in the modern individuals than we did in the plague victims, suggesting this combination could have been disadvantageous for individuals infected with Y. pestis." (PMID 34002224, 2021).
polymyositis (2 papers, 2018 to 2022). A rare idiopathic inflammatory myopathy characterized by symmetric proximal muscle weakness and elevated muscle enzymes. "Recent genetic studies show that the strongest individual allelic associations for polymyositis are with HLA-B*08:01 and another study showed strong HLA-B*08:01 associations with idiopathic inflammatory myopathies." (PMID 29989547, 2018).
posterior uveitis (2 papers, 2022 to 2023). Inflammation of the choroid as well as the retina and vitreous body. "Regarding the relationship between HLA-B*51 and clinical manifestations of BS, we recognized an association between HLA-B*51 and eye involvement (posterior uveitis)." (PMID 37937176, 2023). "HLA-B*51 positivity conferred a risk of posterior uveitis about two times higher than in the case of HLA-B*51 negativity (OR 2.25; CI: 1.28–3.94; P < 0.05)." (PMID 37937176, 2023). "The HLA-B∗35 was the most frequent HLA-B serotype present in panuveitis and posterior uveitis patients." (PMID 35197811, 2022).
preeclampsia (2 papers, 2022 to 2023). Preeclampsia is a hypertensive disorder of pregnancy that is characterized by new-onset hypertension with proteinuria presenting after 20 weeks of gestation, and depending on mild or severe forms may initially present with severe headache, visual disturbances, and hyperreflexia. "Importantly, this study also showed that HLA-B variants are associated with preeclampsia, and a genome-wide analysis of more than 7,000 preeclampsia cases revealed a 7% increased risk of PE when the HLA-B allele was unfavorable for NKG2A education." (PMID 35720413, 2022). "Mismatches in HLA-B eplets: 65QIA+76ESN, 70IAO, 180E, HLA-C eplets: 193PL3, 267QE, and HLA-DRB1 eplet: 16Y were associated with a mild outcome of preeclampsia if the complication occurred." (PMID 38022600, 2023).
respiratory failure (2 papers, 2021 to 2023). The significant impairment of gas exchange within the lungs resulting in hypoxia, hypercarbia, or both, to the extent that organ tissue perfusion is severely compromised. "For example, this year, a commonly used antibiotic “trimethoprim-sulfamethoxazole” was found to trigger an extremely rare and lethal type of respiratory failure that appears to be generated exclusively in individuals carrying the C*07:02 allotype and its paralogue HLA-B*07:02." (PMID 37465164, 2023).
thymoma (2 papers, 2024 to 2025). A neoplasm arising from the epithelial cells of the thymus. "Among non-thymoma patients (n=14), the frequency of HLA-DQB1 03:03 (25% vs 15.9%, P = 0.195), HLA-C 01:02 (25% vs 15.9%, P = 0.195), HLA-B*52:01 (7.1% vs 3%, P = 0.669) was higher than that in the normal population, the difference was also not statistically significant." (PMID 41357573, 2025). "Among thymoma patients (n=9), the frequency of HLA-DQB1 03:03 (33.3% vs 15.9%, P = 0.057), HLA-C 01:02 (27.8% vs 15.9%, P = 0.167), HLA-B*52:01 (5.6% vs 3%, P = 1.0) was higher than that in the normal population, but the difference was not statistically significant." (PMID 41357573, 2025).
toxoplasmosis (2 papers, 2015 to 2020). A parasitic disease contracted by the ingestion or fetal transmission of toxoplasma gondii. "We demonstrate protection of HLA-A*11:01, HLA-A*02:01, and HLA-B*07:02 mice against toxoplasmosis by (i) this novel chimeric polypeptide, containing epitopes that elicit CD8+ T cells, CD4+ T helper cells, and IgG2b antibodies, and (ii) adjuvant activation of innate immune TLR4 and TLR5 pathways." (PMID 33046728, 2020).
Achilles tendinitis (1 paper, 2023). "Hundreds of alleles of HLA-B are known, and HLA-B27 is associated with Achilles tendinitis." (PMID 37946221, 2023).
acute kidney injury (1 paper, 2021). Sudden and sustained deterioration of the kidney function characterized by decreased glomerular filtration rate, increased serum creatinine or oliguria. "Our pioneering works showed that HLA-B*08 and DRB1*0301 are likely to have the most severe form of the PUUV infection with lower blood pressures, more severe thrombocytopenia, and acute kidney injury (AKI)." (PMID 34452318, 2021).
anaphylaxis (1 paper, 2025). An acute hypersensitivity reaction that occurs from exposure to an allergen. "HLA association analysis identified HLA‐B*07:02 as a potential risk allele and HLA‐C*01:02 as a possible protective allele in cefaclor‐induced anaphylaxis." (PMID 40974473, 2025). "Among these, the HLA‐B*07:02 was significantly associated with an increased risk of anaphylaxis, being present in 5 out of 33 patients but absent in all 41 tolerant controls (p = 0.015; OR = 7.15; 95% CI, 1.22–353.85)." (PMID 40974473, 2025).
anemia (1 paper, 2013). A reduction in the number of red blood cells, the amount of hemoglobin, and/or the volume of packed red blood cells. "Laboratory exams revealed highly elevated inflammatory markers, slightly enhanced IgA and C4 complement titer, mild normochromic anemia, and prolonged partial thromboplastin time as well as the identification of HLA-B*51 and B*27 haplotypes." (PMID 24151511, 2013). "Laboratory findings were characterized by moderately elevated inflammatory markers and mild normochromic anemia, while the immunological tests identified the HLA-B*51 haplotype and enhanced C4 complement titer, with negative results for the autoantibodies testing." (PMID 24151511, 2013).
anxiety disorder (1 paper, 2022). A category of psychiatric disorders which are characterized by anxious feelings or fear often accompanied by physical symptoms associated with anxiety. "In the case of individuals with emotional distress at a medium or high level, the presence of alleles -HLA-A*32, HLA-B*52, and HLA-C*12 was predominantly observed, which could indicate that individuals who are carriers of these alleles have a higher risk of developing anxiety disorders." (PMID 36231907, 2022).
Buerger's disease (1 paper, 2020). "The aim of this study was to investigate the human leukocyte antigen (HLA) class I (HLA‐A and HLA‐B) and II (HLA‐DRB1) allele and haplotype frequencies in a group of Iranian patients with Buerger's disease (BD) in comparison with a normal healthy control group." (PMID 32567246, 2020).
childhood asthma (1 paper, 2025). "However, our findings did not reveal any associations between the 6p.21 region (HLA‐B, HLA‐C, HLA‐DQA1, and HLA‐DQB) and childhood asthma, despite previous reports suggesting such an association." (PMID 40133993, 2025).
chondrosarcoma (1 paper, 2021). A malignant cartilaginous matrix-producing mesenchymal neoplasm arising from the bone and soft tissue. "Analysis of conventional chondrosarcoma showed that β2m expression is positively and significantly correlated with that of HLA-A heavy chain (Spearman’s coefficient of 0.72, p<0.0001) and of HLA-B, -C heavy chain (Spearman’s coefficient of 0.79, p<0.0001)." (PMID 33912442, 2021). "In dedifferentiated chondrosarcoma, HLA-A heavy chain expression was scored positive in 85% (17 out of 20 tumors analyzed) and heterogeneous in 15% (3 out of 20 tumors analyzed) of the tumors, HLA-B, -C heavy chain expression was scored positive in 100% of the tumors (20 out of 20 tumors analyzed)." (PMID 33912442, 2021).
chronic hepatitis (1 paper, 2013). An active inflammatory process affecting the liver for more than six months. "We therefore investigated 16 KIR genotypes along with HLA-B and -C ligands and a genetic variant of interleukin (IL) 28B (rs8099917) in 115 chronic hepatitis C genotype 1 patients who underwent pegylated-interferon-α2b (PEG-IFN) and ribavirin therapy." (PMID 24349500, 2013).
colon adenocarcinoma (1 paper, 2019). "In addition, ALPHLARD-NT identified 88 HLA somatic mutations, including recurrent mutations and a novel HLA-B type, from WES data of 343 colon adenocarcinoma cases." (PMID 30942618, 2019).
colorectal tumor (1 paper, 2019). "Kaplan Meier survival curve showed the expression of HLAB, 14-3-3β, ADAMTS2, LTBP3, NME2 and JAG2 on colorectal tumour cells associated with CRC specific survival." (PMID 30679934, 2019). "Our study showed that colorectal tumor which did not metastasize had stronger expression of HLAB than tumor which metastasis." (PMID 30679934, 2019).
complication (1 paper, 2008). Any disease or disorder that occurs during the course of, or because of, another disease, treatment, or procedure. "HLA-B*5901 exhibited a high odds ratio for SJS/TEN with ocular complications (carrier frequency: p<0.05, Pc=0.42, OR=7.0; allele frequency: p<0.05, Pc=0.46, OR=6.7)." (PMID 18385790, 2008).
congenital adrenal hyperplasia (1 paper, 2023). Congenital adrenal hyperplasia (CAH) is an inherited endocrine disorder caused by a steroidogenic enzyme deficiency that is characterized by adrenal insufficiency and variable degrees of hyper or hypo androgyny manifestations, depending of the type and the severity of the disease. "The link between specific human leukocyte antigen (HLA)-B genes and congenital adrenal hyperplasia (CAH) has been a subject of interest." (PMID 37033531, 2023).
congenital hypothyroidism (1 paper, 2018). A thyroid hormone deficiency present from birth. "Thus, this comparison included (i) trastuzumab/HER2 testing for targeted oncology therapy, (ii) HLA-B*15:02 screening for PGx testing, and (iii) congenital hypothyroidism screening for newborn screening." (PMID 30367635, 2018). "Unlike trastuzumab/HER2 testing and congenital hypothyroidism screening are provided routinely in all focus countries, HLA-B*15:02 screening is available as the standard care in Singapore and Thailand, but not in Malaysia and Indonesia despite the high allele frequency in SEA (> 15%)." (PMID 30367635, 2018).
Cryptosporidium infection (1 paper, 2021). "In this current study HLA-B*38:02 and HLA-DQA1*01:01 were associated with increased risk of Cryptosporidium infection." (PMID 33910121, 2021). "Moreover, we previously identified associations between alleles HLA-B*15, HLA-DQB1*03:01 and haplotype HLA-DRB1*11:01/HLA-DQB1*03:01 with increased incidence of asymptomatic and symptomatic Cryptosporidium infection." (PMID 33910121, 2021).
Embryonal tumors (1 paper, 2025). "Embryonal tumors (ATRT, ETMR, MRT, and medulloblastoma) were with similarly low expression levels, with medians spanning 6.0–7.2 for HLA-A, 3.9–6.5 for HLA-B, and 5.9–8.0 for HLA-C, indicating limited HLA class I-mediated immune visibility." (PMID 41312385, 2025).
enthesitis related arthritis (1 paper, 2010). "Among all the patients enthesitis related arthritis most commonly occurred in patients with HLAB*2705 allele (OR = 2.01, p < 0.02), oligoarthritis in patients with *2710 allele (OR = 3.0, p < 0.04) and polyarthritis with *2717 allele (OR = 3.0, p < 0.05)." (PMID 20946671, 2010). "Our findings indicate a trend to have HLAB 27 positive JIA in children over 7 years of age and the most common type is enthesitis related arthritis." (PMID 20946671, 2010).
fish disease (1 paper, 2022). Diseases of freshwater, marine, hatchery or aquarium fish. "As a result, the peptide with excellent binding capacities to HLA-A*0201, HLA-B*3501, and HLA-B*3508 might be employed as efficient vaccinations against certain fish diseases." (PMID 35399010, 2022).
glomerulonephritis (1 paper, 2012). A renal disorder characterized by damage in the glomeruli. "Individuals from the glomerulonephritis group possessing both variants of KIR2DS4 and perfect HLA-B,-DR matching had about 15 times higher chance of rejection than analogous persons from the non-glomerulonephritis group (both panels)." (PMID 23028591, 2012). "Namely, in the non-glomerulonephritis group, HLA-B,-DR matching seemed to be much more important for acute graft rejection than the presence or absence of KIR2DS4 gene variants." (PMID 23028591, 2012). "The lack of strong association of graft rejection with HLA-B,-DR mismatching in recipients with glomerulonephritis could not have been observed in earlier studies done without stratification for the presence or absence of KIR2DS4 gene." (PMID 23028591, 2012). "In our study, we observed a strong effect of KIR2DS4 variants in patients with glomerulonephritis, where HLA-B,-DR mismatch exerted much weaker influence on the graft fate, whereas in recipients without glomerulonephritis the effect of HLA-mismatch was predominant." (PMID 23028591, 2012).
graft versus host disease (1 paper, 2016). An immune system disorder that occurs after allogeneic hematopoietic stem cell transplant and is a reaction of donor immune cells against host tissues. "The pathway enrichment for trans-eQTL egenes was largely driven by HLA genes (e.g. HLA-DRB4, HLA-C, HLA-B, HLA-DPA1, and HLA-DQA1 appear in the gene sets for graft-versus-host disease, allograft rejection, and cell adhesion molecules)." (PMID 27140173, 2016).
heart failure (1 paper, 2021). Inability of the heart to pump blood at an adequate rate to meet tissue metabolic requirements. "In addition, HLA‐A and HLA‐B also play potential roles in heart failure." (PMID 33230903, 2021).
Hodgkins lymphoma (1 paper, 2024). A heterogeneous group of malignant lymphoid neoplasms of B-cell origin characterized histologically by the presence of Hodgkin and Reed-Sternberg (HRS) cells in the vast majority of cases. "Fifty years since the first report on the association between HLA-B and Hodgkin’s lymphoma, HLA alleles have been associated with a great number of human diseases, proving that HLA molecules are essential for protective immunity and for deleterious, disease-causing autoimmune reactivity." (PMID 39835139, 2024).
Hyperbilirubinemia (1 paper, 2021). An increased amount of bilirubin in the blood. "Additionally, patients with both elevated ALT and hyperbilirubinemia were analyzed for HLA-B*57:01 and UGT1A1 variants." (PMID 33805415, 2021).
iritis (1 paper, 2022). Inflammation of the iris. "The significant PRS models have a wide range of the number of variables selected in the model, ranging from only one variable for iritis PRS (HLA allelotype, HLA-B*27:05, at the well-established HLA-B*27 locus) to 51,209 variants selected for standing height PRS." (PMID 35324888, 2022).
kidney stones (1 paper, 2025). "Female sex, HLA-B*57:01 genotype, and pre-existing kidney stones have also been associated with elevated risk for hepatotoxicity during flucloxacillin treatment." (PMID 40434591, 2025).
leishmaniasis (1 paper, 2025). Infectious disease that is transmitted through the bite of hematophagous female phlebotomine sand flies. "HLA-B*38 has been linked either with protection against leishmaniasis or risk of severe COVID-19 infection." (PMID 40284905, 2025).
liver cancer (1 paper, 2011). An epithelial or non-epithelial malignant neoplasm that arises from the liver.
liver toxicity (1 paper, 2017). "HLA-B*57 was significantly associated with cholestatic (P = 0.001) and mixed (P = 0.017) types of liver toxicity, and mild-to-moderate severity (P = 0.001)." (PMID 28289388, 2017). "The proportion of HLA-B*57 allele carriers in Ethiopian patients who developed anti-TB and ARV drugs induced liver toxicity (37.0%), particularly in those who developed cholestatic type of liver toxicity (44.8%) was significantly higher compared with those who tolerated the treatment (2.2%)." (PMID 28289388, 2017).
Löfgren’s syndrome (1 paper, 2023). "HLA-B*08:01, HLA-C*07:01, HLA-DRB1*03:01, HLA-DQA1*05:01, and HLA-DQB1*02:01 variants associated with Löfgren’s syndrome, a more benign phenotype." (PMID 37153085, 2023).
malignant hypertension (1 paper, 2023). Severe hypertension that is characterized by rapid onset of extremely high blood pressure and hypertension-mediated organ damage. "Associations with HLA-B*35 were also reported by Forsberg and Lowe in patients with malignant hypertension and terminal uremia." (PMID 37686189, 2023).
mental disorder (1 paper, 2022). A disease that has its basis in the disruption of mental process. "Of the 39 PGx drugs, nine drugs (23%) with more than one actionable DGI,including genes coding forCYP2D6, CYP2C19, HLA-A, HLA-B, CYP2C9, CYP4F2or VKORC1 were used by 3.9% of the PGx drug users of the population and9.7% of the PGx drug users of the combined mental disorders casecohorts." (PMID 34753194, 2022).
mesothelioma (1 paper, 2025). A usually malignant and aggressive neoplasm of the mesothelium which is often associated with exposure to asbestos. "Therefore, increased ISG signaling may predispose mesothelioma towards increased HLA-B and -C expression, consistent with our immunopeptidomics analysis." (PMID 39921204, 2025).
metabolic syndrome (1 paper, 2013). A cluster of metabolic risk factors for CARDIOVASCULAR DISEASES and TYPE 2 DIABETES MELLITUS. "Metabolic syndrome was associated with the presence of HALS (47.1% vs. 35.6%, OR = 1.61; 95%CI: 1.01.2.57, P = 0.0446) and with carriage of the HLA-B*40∶01 genotype (7.8% vs. 2.1%, OR = 4.04; 95%CI: 1.16–17.71, P = 0.0244)." (PMID 23840581, 2013).
mucocutaneous leishmaniasis (1 paper, 2013). The most common form of leishmaniasis that is transmitted through the bite of female phlebotomine sand flies or after exposure to leishmania parasites. "The present study sought to investigate the association between HLA-A, HLA-B and HLA-DRB1 genes and susceptibility or resistance to the different clinical manifestations of American cutaneous leishmaniasis (ACL) in southern Brazil." (PMID 23638805, 2013).
mumps (1 paper, 2021). "Selected epitopes were tested for their capacity to recall a specific T cell response, by using expanded CD8 + T-effector cells isolated from three HLA-B*07:02 positive and three HLA-A*01:01 positive mumps patients." (PMID 34211021, 2021). "Subsequently, APIQGTNLL, KPRTSTPVTEF, IPNARANL (HLA-B*07:02 restricted epitopes), and YSDPNNHEVY and VTDSNLIY (HLA-A*01:01 restricted epitopes) were selected for custom-made (p:HLA) dextramer synthesis to investigate the ex vivo occurrence of CD8+ T cells against these epitopes in mumps patients." (PMID 34211021, 2021).
myxoid liposarcoma (1 paper, 2022). A liposarcoma characterized by the presence of round non-lipogenic primitive mesenchymal cells and small signet ring lipoblasts within a myxoid stoma with a branching vascular pattern. "Results identified a common haplotype HLA-A 24* and HLA-B73* that was strongly down-regulated compared to healthy tissues, and a genetic deletion of the HLA-B locus in some myxoid liposarcoma (MLPS)." (PMID 35884474, 2022).